CYRIB (CYFIP related Rac1 interactor B)
Description:
Negatively regulates RAC1 signaling and RAC1-driven cytoskeletal remodeling. Regulates chemotaxis, cell migration and epithelial polarization by controlling the polarity, plasticity, duration and extent of protrusions. Limits Rac1 mediated activation of the Scar/WAVE complex, focuses protrusion signals and regulates pseudopod complexity by inhibiting Scar/WAVE-induced actin polymerization. Protects against Salmonella bacterial infection. Attenuates processes such as macropinocytosis, phagocytosis and cell migration and restrict sopE-mediated bacterial entry. Also restricts infection mediated by Mycobacterium tuberculosis and Listeria monocytogenes (By similarity). Involved in the regulation of mitochondrial dynamics and oxidative stress.
Synonyms: CYRI; FAM49B; BM-009; CYRI-B; L1
Tractability: Small molecule: a structure with a bound ligand is known. Antibody: its Gene Ontology location is reachable by antibodies, with high confidence. PROTAC: UniProt records ubiquitination sites on it; ubiquitination databases record sites on it.
Gene: Protein-coding gene on chromosome 8 (129,839,593 to 130,017,504, reverse strand). Ensembl gene ENSG00000153310.
Subcellular location: Membrane; Mitochondrion
Subcellular location (Human Protein Atlas): Nucleoplasm; Cytosol
Pathways (Reactome):
Hemostasis: Platelet degranulation
Gene Ontology:
Molecular function: protein binding; small GTPase binding; MHC class Ib protein binding, via antigen binding groove
Biological process: cellular response to molecule of bacterial origin; negative regulation of actin filament polymerization; negative regulation of small GTPase mediated signal transduction; regulation of cell migration; regulation of chemotaxis; regulation of establishment of cell polarity; regulation of mitochondrial fission; positive regulation of memory T cell activation; positive regulation of T cell activation; positive regulation of T cell mediated cytotoxicity; positive regulation of type II interferon production; regulation of actin filament polymerization
Cellular component: extracellular exosome; mitochondrion; cilium; extracellular region; platelet alpha granule lumen; membrane
Genetic constraint (gnomAD): Loss-of-function variants: 4 observed, 22.73 expected, observed/expected ratio (o/e) 0.18, 90% interval 0.086 to 0.4. The upper end of that interval is the gene's LOEUF score, 0.4, which puts it in group 1 of 6, group 1 being the genes least tolerant of losing a copy. Missense variants: 104 observed, 214.51 expected, observed/expected ratio (o/e) 0.48, 90% interval 0.41 to 0.57. Synonymous variants: 80 observed, 75.84 expected, observed/expected ratio (o/e) 1.05, 90% interval 0.88 to 1.27.
Homologues: Orthologues: chimpanzee CYRIB (100% identical), guinea pig CYRIB (100% identical), macaque CYRIB (100% identical), rabbit CYRIB (100% identical), mouse Cyrib (99% identical), dog CYRIB (97% identical), rat Cyrib (97% identical), tropical clawed frog cyrib (93% identical), zebrafish fam49bb (88% identical), zebrafish fam49ba (78% identical), Drosophila melanogaster CG32066 (55% identical), Caenorhabditis elegans R07G3.8 (36% identical). Paralogues in human: CYRIA (79% identical).
Diseases named in the same sentence as CYRIB in open-access papers:
CYRIB is named in the same sentence as 23 diseases in open-access papers, as found by Europe PMC text mining. Sharing a sentence is not in itself a finding about the gene and the disease. The quoted sentences say what the papers report.
breast cancer (6 papers, 2018 to 2025). A primary or metastatic malignant neoplasm involving the breast. "GLS, YY1AP1, FBXO22, KLC1, CUL4A, KITLG, and CYRIB are changed by AS that may be linked to the emergence of breast cancer." (PMID 40384436, 2025).
pancreatic cancer (3 papers, 2021 to 2025). "CYRIB mediates pancreatic cancer's growth and signaling; downregulation of CYRIB promotes tumor cell migration, invasion, and EMT." (PMID 40384436, 2025).
Salmonella Infections (2 papers, 2019 to 2025). Infections with bacteria of the genus SALMONELLA. "Furthermore, CYRIB is involved in the regulation of memory T cell activation, and PFN1 is involved in the Rap1 signaling pathway, regulation of the actin cytoskeleton, and response to salmonella infection." (PMID 41026719, 2025).
tumor (15 papers, 2010 to 2025). "No study has investigated the role of the CYRIB gene in tumor progression." (PMID 35692877, 2022).
CYRIB also shares sentences with these, for which no sentence is quoted: cancer (15 papers); gallbladder cancer (5); pancreatic ductal adenocarcinoma (5); colorectal cancer (3); liver cancer (3); hepatocellular carcinoma (2); infection (2); melanoma (2); autoimmune disease (1); bacterial infection (1); lung adenocarcinoma (1); lymphopenia (1); metastatic disease (1); myocardial ischemia (1); Obesity (1); oral cancer (1); prostate carcinoma (1); sarcoma (1); T cell deficiency (1).